CCDC7 (coiled-coil domain containing 7)
Description:
May play a role in tumorigenesis.
Synonyms: BIOT2; C10orf68; FLJ32762; FLJ13031; BioT2-A; BioT2-B; BioT2-C
Tractability: No criterion of Open Targets' tractability assessment is met for any kind of drug.
Gene: Protein-coding gene on chromosome 10 (32,446,140 to 32,882,874, forward strand). Ensembl gene ENSG00000216937.
Subcellular location (Human Protein Atlas): Nucleoli; Cytosol; Mitotic spindle
Genetic constraint (gnomAD): Loss-of-function variants: 79 observed, 86.03 expected, observed/expected ratio (o/e) 0.92, 90% interval 0.76 to 1.11. The upper end of that interval is the gene's LOEUF score, 1.11, which puts it in group 4 of 6, group 1 being the genes least tolerant of losing a copy. Missense variants: 736 observed, 736.13 expected, observed/expected ratio (o/e) 1, 90% interval 0.94 to 1.06. Synonymous variants: 274 observed, 252.73 expected, observed/expected ratio (o/e) 1.08, 90% interval 0.98 to 1.2.
Homologues: Orthologues: chimpanzee CCDC7 (99% identical), macaque CCDC7 (91% identical).
Diseases named in the same sentence as CCDC7 in open-access papers:
CCDC7 is named in the same sentence as 12 diseases in open-access papers, as found by Europe PMC text mining. Sharing a sentence is not in itself a finding about the gene and the disease. The quoted sentences say what the papers report.
cervical cancer (3 papers, 2023 to 2024). A primary or metastatic malignant neoplasm involving the cervix. "It was reported that the upregulated gene CCDC7 was intimately associated with the development of cervical cancer." (PMID 37679400, 2023). "The CCDC7 gene was associated with the development of human cervical cancer and colorectal cancer." (PMID 38540995, 2024).
colorectal cancer (2 papers, 2020 to 2024). A primary or metastatic malignant neoplasm that affects the colon or rectum. "In the 10p11.22, CCDC7, also known as Biot2, highly expressed in CD133-positive stem cells, functions as a risk factor for poor prognosis in colorectal cancer." (PMID 32923390, 2020).
chronic fatigue syndrome (1 paper, 2025). "CCDC7 has a high frequency of SNPs in myalgic encephalomyelitis/chronic fatigue syndrome." (PMID 40943121, 2025).
preeclampsia (1 paper, 2024). Preeclampsia is a hypertensive disorder of pregnancy that is characterized by new-onset hypertension with proteinuria presenting after 20 weeks of gestation, and depending on mild or severe forms may initially present with severe headache, visual disturbances, and hyperreflexia. "First, our study focused on rare variants of preeclampsia offspring, and both of these two rare variants of CCDC7 were maternal." (PMID 38540995, 2024). "In conclusion, CCDC7 is a potential susceptibility gene for preeclampsia, which is key for the migration and invasion of trophoblast cells." (PMID 38540995, 2024). "In this study, we detected two rare CCDC7 variants in the preeclampsia offspring from two unrelated families and found that CCDC7 had a crucial role in the development of preeclampsia by regulating the migration and invasion of trophoblast cells." (PMID 38540995, 2024). "In our study, we found that rare variants of CCDC7 disturbed the migration and invasion of trophoblast cells and contributed to the development of preeclampsia, which further indicates a role of rare variants in the offspring of mothers with preeclampsia." (PMID 38540995, 2024). "In this study, we detected two rare variants of CCDC7 in the offspring of two preeclampsia families and found that the knockdown of CCDC7 impaired the migration and invasion of trophoblast cell." (PMID 38540995, 2024). "Further investigations on the mechanism are needed for a better understanding of the function of CCDC7 and the molecular mechanism of preeclampsia caused by loss-of-function mutations in the CCDC7 gene." (PMID 38540995, 2024). "To investigate whether these variants detected in our study affected CCDC7 localization and expression, we compared CCDC7 localization and expression in the placentas from two preeclampsia families with age-matched controls." (PMID 38540995, 2024). "Collectively, these results imply that CCDC7 is involved in the pathology of preeclampsia." (PMID 38540995, 2024). "Therefore, further study may be needed on the role of rare variants of CCDC7 on the maternal syndrome, although preeclampsia did not occur in all pregnancies of women carrying rare variants of CCDC7." (PMID 38540995, 2024).
cancer (3 papers, 2013 to 2025). A tumor composed of atypical neoplastic, often pleomorphic cells that invade other tissues. "The CCDC7 gene (coiled-coil domain containing 7) seems to be associated with human cancer, and there is no information available for bovines." (PMID 23738659, 2013).
CCDC7 also shares sentences with these, for which no sentence is quoted: prostate carcinoma (2 papers); tumor (2); breast carcinoma (1); breast invasive carcinoma (1); head and neck squamous cell carcinoma (1); lung adenocarcinoma (1); Lung squamous cell carcinoma (1).